ERG (ETS transcription factor ERG)
Diseases named in the same sentence as ERG in open-access papers (continued):
Sharing a sentence is not in itself a finding about the gene and the disease.
prostate carcinoma (continued). "The weights of the prostate glands and the incidence of prostate carcinoma were significantly decreased in PB-Cre4/Ptenfl/fl/ERG/Snd1fl/fl males." (PMID 37973913, 2023). "More specifically, when IDCP expressed ERG, the adjacent invasive prostate cancer was also ERG-positive with low-grade features." (PMID 37185705, 2023). "We have previously shown that expression of ERG can promote migration of PC3 prostate cancer cells, and migration of PC3-ERG cells was also decreased by PABPC1 knockdown." (PMID 37956771, 2023). "3ʹUTR of ERG plays a significant role in the modulation of ERG expression and function in prostate cancer by providing binding sites to miRNAs." (PMID 37310937, 2023). "PTEN deletion and ERG rearrangement exhibit a significant role in the pathogenesis and clinical course of prostate cancer, and both represent frequent genetic alterations." (PMID 37185705, 2023). "They observed that among Caucasian patients, ERG expression followed a positive trend from HGPIN (17.5%) to clinically localized prostate cancer (33%) and metastases (53%) (p = 0.01)." (PMID 37511059, 2023). "Here, the authors report an interaction between ERG and SND1 as necessary for ERG-driven prostate cancer initiation using preclinical models." (PMID 37973913, 2023). "In conclusion this is the first study investigating that miR-4482 and miR-3912 suppress the ERG expression and its target genes, and thereby halt the prostate cancer progression." (PMID 37310937, 2023). "Although considered an early event in prostate cancer, ERG gene fusions and overexpression can be detected in advanced disease, with only a modest decrease in frequency compared to primary PCa." (PMID 35267426, 2022). "ChIP-seq analyses for several ETS members in prostate cancer cells identified overrepresentation of the AP-1 binding site in regions occupied by ERG, ETV1 and ETV4." (PMID 35267426, 2022). "We previously reported that ERG subtypes of prostate cancer have altered androgen receptor signaling, similar to the ETV4 subtypes of prostate cancer shown in the current study." (PMID 36289913, 2022). "This is accompanied by the loss of DNA binding of several key transcription factors in prostate cancer progression, including the AR, FOXA1 and ERG." (PMID 36212399, 2022). "To investigate cellular signaling pathways related to S:E fusion-positive prostate cancer, we identified genes significantly correlated with ERG expression in S:E fusion-positive prostate cancer via the Pearson correlation test." (PMID 36579559, 2022). "ERG rearrangements result in ERG overexpression; thus, we previously thought that cellular signaling pathways both in S:E fusion-positive prostate cancer and T:E fusion-positive prostate cancer were alike." (PMID 36579559, 2022). "In conclusion, when heterogeneity is considered, ERG protein is a robust prognostic biomarker for prostate cancer." (PMID 35574900, 2022). "Additional studies using prostate cancer models showed phosphorylation of ERG at residues in the N-terminal degron by casein kinase I δ, which triggers ubiquitination by the Cullin3-SPOP E3 ubiquitin ligase complex and consequent degradation." (PMID 35267426, 2022). "HDACs were shown to be highly expressed and necessary for ERG activity in advanced prostate cancer models." (PMID 35267426, 2022). "Its application to allele-specific information from the primary localized prostate cancer TCGA dataset (PRAD) and from the mCRPC collection from the SU2C dataset nominated mutually exclusive or co-occurrent aberrations with ERG fusion events." (PMID 35267426, 2022).
prostate carcinoma (continued). "FZD8, the highest ERG-correlated gene (R = 0.761) in S:E fusion-positive prostate cancer, is involved in bone metastasis in prostate cancer." (PMID 36579559, 2022). "Frizzled receptors such as FZD4, which has been found to mediate EMT in prostate cancer cells, have been found to also be upregulated by ERG and to contribute to increased Wnt signalling activity." (PMID 35563163, 2022). "Mass spectrometry analysis using the VCaP prostate cancer cell line confirmed the phosphorylation at serine 215 and identified serine 81 as a newly phosphorylated residue in the ERG protein." (PMID 35267426, 2022). "In 2005, seminal work by Tomlins and colleagues identified gene fusions between the AR-regulated gene TMPRSS2 and ERG in a large subset of prostate cancer samples." (PMID 35267426, 2022). "We ranked our tools based on their accuracy to detect the fusion TMPRSS2:ERG in each of the prostate cancer cell lines, together with ease of use and the total time required." (PMID 35625354, 2022). "In that study, TAK-242-attenuated prostate cancer cell migration was shown to be dependent on ERG (transcription factor) activated TLR4 gene expression." (PMID 36232715, 2022). "Genomic, molecular and biochemical studies have shed light on the mechanisms inducing the fusion formation and the role of ERG in the early steps of the genesis of prostate cancer and in the advanced stages of the disease." (PMID 35267426, 2022). "ERG has been shown to upregulate ADAMTS1 genes in prostate cancer cells, which show an attraction towards fibroblasts." (PMID 35563163, 2022). "T:E fusion-positive prostate cancer was obtained by considering fusions of exon 1 of TMPRSS2 to exon 4 or exon 5 of ERG (n = 86) because exon 4 or exon 5 of ERG are the most abundant breaking sites, generating T:E fusions." (PMID 36579559, 2022). "SCL45A3 is an androgen-regulated gene that, like TMPRSS2, is seen as a recurrent fusion partner with ERG in prostate cancer." (PMID 36337169, 2022). "For instance, a prospective study reported that vigorous exercise was associated with reduced risk of advanced and lethal prostate cancer and a lower risk of the TMPRSS2:ERG fusion-positive disease." (PMID 35326519, 2022). "ERG gene rearrangement is known to contribute to the pathogenesis of prostate cancer and provides important clues about the multifocality and metastatic dissemination of this disease." (PMID 35513774, 2022). "SLC45A3:ERG (S:E) fusion is found in approximately 6% of ERG fusion prostate cancer, and concurrent TMPRSS2 and SLC45A3 fusions to ERG are found in 11% of ERG fusion-positive cancer." (PMID 36579559, 2022). "Clinical data demonstrate the incidence of ERG overexpression in approximately 50% of all patients diagnosed for prostate cancer." (PMID 35563163, 2022). "In this study, we demonstrated that a digitized H&E-stained slide analyzed using a deep learning-based model can successfully predict ERG fusion status in the majority of prostate cancer cases." (PMID 35513774, 2022). "TMPRSS2:ERG fusions are a common genomic alteration in prostate cancer; however, variations in its incidence have been extensively observed." (PMID 35625354, 2022). "The gene fusion product transmembrane-protease-serine-2 (TMPRSS2)-ETS-related gene (ERG) as a result of chromosomal translocation is observed in 20 to 50% of prostate cancer patients with different ethnicities." (PMID 35547880, 2022). "Our study provides a viable and inexpensive alternative to ancillary tissue-based testing methods to detect ERG rearrangement status in prostate cancer." (PMID 35513774, 2022). "ERG oncogenic activity characterizes several malignancies, including Ewing’s sarcoma, leukemia and prostate cancer (PCa)." (PMID 35267426, 2022). "To conclude, we investigated the molecular features defined by different fusion partners of ERG in prostate cancer." (PMID 36579559, 2022).
prostate carcinoma (continued). "ERG is also known to be fused to transmembrane protease serine 2 (TMPRSS2) in prostate cancer cells, resulting in ERG overexpression." (PMID 35723257, 2022). "Fortunately, cancer driver genes in prostate cancer, ERG, ETV1, ETV4, SPOP, and FOXA1, have been identified and their roles have been proved through basic and clinical research." (PMID 36579559, 2022). "PGC1α acts as a co-activator of the ERG transcription factor during metabolic stress resulting in antioxidant functionsand inhibition of the PGC1α-ERG driven transcriptional program reduces prostate cancer growth by inducing ROS mediated apoptosis." (PMID 35508713, 2022). "In prostate cancer cells, ERG overexpression increases the rate of epithelial to mesenchymal transitions via the EMT pathway, enhancing the ability of PCa cells to invade and metastasize." (PMID 35563163, 2022). "The present study shows that substantial tumor heterogeneity necessitates analyses of multiple malignant areas to fully appreciate the prognostic impact of ERG protein in prostate cancer." (PMID 35574900, 2022). "To address this, we examined the interactivity between the ATAD1 promoter and ERG by accessing the GSE55062 dataset that conducted chromatin immunoprecipitation (ChIP) assay in human prostate cancer cell line VCaP." (PMID 36362897, 2022). "Rearrangements between TMPRSS2, encoding an androgen-regulated protease, and ERG, an ETS transcription factor, are among the most common somatic alterations in human prostate cancers." (PMID 35104804, 2022). "The Tumor Fusion Gene Data Portal website was used to identify prostate cancer with structural variation of ERG." (PMID 36579559, 2022). "The translation of the ERG gene gives rise to different fusion gene products, such as TMPSSR2-ERG and NDRG1-ERG in prostate cancer, EWS-ERG in Ewing’s sarcoma, and FUS-ERG in acute myeloid leukemia." (PMID 36009466, 2022). "The urine-exosome signature is derived from genes known to play a role in prostate cancer initiation and progression, including ERG, PCA3, and SPDEF." (PMID 34593984, 2022). "In leukemia and prostate cancer cells, interaction between ERG and bromodomain containing protein 4 (BRD4) has been observed." (PMID 35267426, 2022). "Global transcriptomic profiling with RNA sequencing (RNA-seq) revealed significant downregulation of AR and FOXA1-regulated genes in multiple prostate cancer cells, as well as ERG-regulated transcripts in ERG fusion-positive VCaP cells." (PMID 34937944, 2022). "In prostate cancer cells, a surprisingly common occurrence involves the fusion of ERG to TMPRSS2, which forms the fusion product of TMPRSS2-ERG." (PMID 35563163, 2022). "Altogether, the overexpression of ERG in prostate cancer is a key modulator of tumor progression and aggressiveness, as it can regulate the transcription of the proteins that mediate inflammation, cell invasion, differentiation, and oncogenesis." (PMID 35563163, 2022). "The best known fusion genes associated with prostate cancer involve ETS transcription factor family members and the androgen-regulated promotor TMPRSS2 (TMPRSS2:ERG, TMPRSS2:ETV1, and TMPRSS2:ETV4)." (PMID 35625354, 2022). "Oppositely to this, the interaction of ERG with FOXO1, a forkhead transcription factor frequently inactivated in prostate cancer, inhibits ERG-mediated transcriptional activation." (PMID 35267426, 2022). "Approximately 40–50% of prostate cancer cases are characterized by ERG gene fusions, which lead to ERG overexpression." (PMID 35267426, 2022). "Previous studies found that ~55% of prostate cancer patients have ERG overexpression driven by fusion of the ERG gene with androgen response genes such as TMPRSS2." (PMID 36579559, 2022). "TMPRSS2:ERG (T:E) fusion is most frequently found in prostate cancer, and its oncogenic role and regulating molecular mechanisms have been well studied." (PMID 36579559, 2022).
prostate carcinoma (continued). "They implanted TMPRSS2: ERG-positive VCaP (cell line of human prostate cancer) onto a fertilized chicken embryo’s upper chicken chorioallantoic membrane (CAM)." (PMID 36476230, 2022). "Recently, an organoid model derived from the Pten-null, ERG-overexpressing mice described by Chen and colleagues was used to investigate the effects of knocking out ERG in the context of Pten-null prostate cancer." (PMID 36212399, 2022). "There have been conflicting reports regarding the prognostic value of ERG gene rearrangement and its overexpression in prostatic cancer." (PMID 35513774, 2022). "In contrast with the consensual isoform, PACE4-altCT was only strongly overexpressed in prostate cancer patients, correlated with ERG expression levels." (PMID 35410344, 2022). "Fusions of androgen-regulated genes with the ETS-related gene ERG are among the most common genomic alterations in prostate cancer." (PMID 36212399, 2022). "PTEN loss is observed more frequently in ERG-positive tumors, and PTEN-deficient prostate cancer has been shown to have an enhanced inflammatory infiltrate, with a greater density of T-cells and a higher expression of immune-related genes." (PMID 35326519, 2022). "In a previous study, ERG upregulation is seen in about half of all prostate cancer patients, and combining human prostate cancer genetics with transgenic mice showed that PTEN loss occurs concomitantly with ERG aberrant expression." (PMID 35163398, 2022). "Moreover, although the results of clinical studies on the prognostic value of ERG fusion detection in PCa patients remain unclear, its potential as diagnostic biomarker is evident as it is specific for prostate cancer and detectable in a non-invasive manner in the urine of patients." (PMID 35267426, 2022). "Accordingly, transcriptomic subtyping of prostate cancer patients’ samples showed enrichment of ERG overexpression in tumors with luminal features." (PMID 35267426, 2022). "ERG-mediated activation of miR-200b/200a/429 expression interferes with prostate cancer proliferation and invasiveness, an effect that implicates the ERG-miR-200 interaction in the indolent behavior of prostate cancer in the majority of patients." (PMID 34884985, 2021). "In primary prostate cancer, the SPINK1+/ERG+ phenotype was shown to be associated with a higher Gleason grade and aggressive subpopulation with a higher risk of lymph node metastases." (PMID 33916984, 2021). "ERG shows nuclear and cytoplasmic expression in several tissues, which has been identified as a key factor for prostate cancer." (PMID 34917613, 2021). "Going further downstream to find effective targets, characterization of the ERG-regulated kinome identified TNIK as a potential therapeutic target in ERG-fusion gene positive prostate cancer." (PMID 33634124, 2021). "Usp9x deubiquitinates and stabilizes the TF, ERG, in prostate, and we previously published that DUB inhibitor (WP1130) has anti-tumor activity in ERG fusion driven prostate cancer." (PMID 33613844, 2021). "The two most common fusion events in prostate cancers involve either ERG (>50% of primary tumor samples) or ETV family transcription factors (<10%)." (PMID 34795215, 2021). "Together these data indicate a mechanistic basis for inhibition of TLR4 signaling as a treatment for ERG-positive prostate cancer." (PMID 33554122, 2021). "TMPRSS2 has an important role in the pathogenesis of COVID‐19, and the abnormal expression of TMPRSS2 or ERG gene fusion is significant regulators of carcinogenesis in prostate cancer." (PMID 33609069, 2021). "For instance, fusions of ETS transcription factor gene ERG with promoter elements of TMPRSS2 are observed in roughly 50% of prostate cancers, as well as MTOR-TP53BP1, SLC45A2-AMACR, and MAN2A1-FER fusions found at lower frequencies." (PMID 34573358, 2021).
prostate carcinoma (continued). "Attard and colleagues used circulating tumor cells (CTCs), primary prostate tumor and CRPC samples from fusion-positive prostate cancers to study the ERG status and expression." (PMID 33634124, 2021). "The data suggest a therapeutic opportunity for SPOP inhibition or high-dose androgen therapy in prostate cancers that express high levels of ERG." (PMID 33531470, 2021). "We have previously reported that ERG can mimic KRAS in prostate cancer cells, whereby both ERG and KRAS activate a similar gene expression program that promotes cell migration." (PMID 33554122, 2021). "Altogether, the data from these latest studies reveal an important role of ERG in the dissemination of metastatic cells, the seeding to the bone as a preferential metastatic site and the generation of metastatic lesions in prostate cancer." (PMID 33634124, 2021). "ERG shows nuclear and cytoplasmic expression in several tissues, and has been identified as a key factor in prostate cancer." (PMID 34917613, 2021). "For example, AR, PTEN, and ERG expression can vary between different regions within the same prostate carcinoma." (PMID 34638309, 2021). "The TMPRSS2:ERG fusion is present in the VCaP prostate cancer cell line and has been more recently well-characterized in this model." (PMID 33634124, 2021). "On the other hand, EV-related biomarkers have been described as highly tumor-specific, reflecting the peculiarities of their tissues of origin; EVs enriched in TMPRSS2:ERG fusion transcript in prostate cancer are an example." (PMID 34445131, 2021). "Compared to TCGA prostate cancer cohort, the Sardinian prostate cancer cohort had a lower rate of ERG fusion but a higher rate of UDP-glucuronosyltransferase family amplification on chromosome 4q13.2." (PMID 33391440, 2021). "This genetic fusion occurs in approximately 50% of prostate cancer cases and results in androgen-driven overexpression of ERG." (PMID 34638309, 2021). "This was particularly curious since AR binding to TMPRSS2 and ERG introns promotes formation of the TMPRSS2/ERG gene rearrangement in prostate cancer." (PMID 34409300, 2021). "We show that Usp9x/DUB inhibitor induced apoptosis in ERG independent prostate cancer lines (DU-145, PC-3 NE-like) and NEPC cell line (H660) through the down regulation of SOX2 and also impedes the formation of colonies in 3D-culture." (PMID 33613844, 2021). "Ewing sarcoma breakpoint region 1 (EWSR1) encodes a multifunctional protein that can cooperate with the transcription factor ERG to promote prostate cancer." (PMID 34409300, 2021). "The only prostate cancer cell line with known ERG dependency is the androgen-dependent cell line VCaP." (PMID 33554122, 2021). "Gene fusions involving the ERG transcription factor and point mutations in the ubiquitin ligase adaptor SPOP are two truncal mutations that are mutually exclusively present in prostate cancer." (PMID 33531470, 2021). "Several other TMPRSS2:ERG fusion events with different junction sites have also been described to occur in prostate cancer clinical samples with lower frequency." (PMID 33634124, 2021). "To assess the feasibility of the O'PROTAC strategy in degrading other TFs, we designed and synthesized O'PROTACs to destruct ERG, which is overexpressed in ≈50% of prostate cancer cases in patients." (PMID 34397171, 2021). "In aggregate, the data support an antagonistic relationship between oncogenic activation of ERG and a loss of SPOP function in prostate cancer cells." (PMID 33531470, 2021). "Other transcription factors that contribute to activate expression of the miR-200b/200a/429 cluster include Smad3, in gastric cancer cells and ERG, in prostate cancer cells." (PMID 34884985, 2021). "The expression of PCAT5 was confirmed in the VCaP prostate cancer cell line harboring the TMPRSS2:ERG fusion and was significantly decreased as a result of siRNA-mediated knock-down of ERG." (PMID 33634124, 2021).